ATM (ATM serine/threonine kinase)
Diseases named in the same sentence as ATM in open-access papers (continued):
Sharing a sentence is not in itself a finding about the gene and the disease.
breast cancer (continued). "Our results justify future clinical work to validate phospho-ATM level in breast cancer tissue as a predictor of PARP inhibitor sensitivity." (PMID 27613518, 2016). "We and others previously showed that ataxia telangiectasia mutated (ATM), a protein that is critical in maintaining genomic stability, is significantly reduced in breast cancer as compared to normal breast tissue." (PMID 27741524, 2016). "Cytotoxicity of PARP inhibitor and ATM inhibitor in breast cancer cell lines was assessed by MTS, colony formation and apoptosis assays." (PMID 27613518, 2016). "Our experiments link levels of phospho-ATM and 53BP1 to Olaparib sensitivity of breast cancer cell lines." (PMID 27613518, 2016). "To examine the relationship between ATM and IL-8 expression and metastasis in human breast cancer, we analyzed a set of expression arrays from 560 breast cancer patients with clinical annotation." (PMID 26030852, 2015). "These investigations should contribute to the understanding of the role played by the ATM gene in the etiology and pathobiology of breast cancer." (PMID 25625042, 2015). "Previous researches demonstrated that DSB-initiated genomic deletion, including ATM, was greatly increased in high-grade breast cancer." (PMID 25861265, 2015). "A variation in breast cancer risk associated with parity has been evidenced according to the type of mutation in the DNA repair gene BRCA1, acting in the same pathway as ATM." (PMID 25879635, 2015). "Reduced levels of ATM mRNA and protein have also been reported in sporadic breast tumors, implicating ATM gene inactivation in the development and progression of breast cancer." (PMID 25625042, 2015). "Consistent with the biological relevance of these findings, ATM promoted tumor formation in a xenograft human breast cancer cell model." (PMID 26030852, 2015). "The levels of ATM and the poor prognosis of the disease have been reported previously.Hence the increase in ATM expression upon chimeric construct treatment is an interesting finding for molecular mechanism in breast cancer." (PMID 26176230, 2015). "Collectively, these results demonstrate that ATM can play dual functions in breast cancer tumor progression." (PMID 26030852, 2015). "In vitro studies have shown that lymphocytes from ATM mutation-carriers are more radiosensitive than lymphocytes from normal donors, suggesting that even low radiation dosages might be deleterious for such individuals, increasing their risk for breast cancer or inducing severe complications." (PMID 25625042, 2015). "Germ line point mutations in ATM and PTEN have been reported to play a role in breast cancer predisposition." (PMID 24884479, 2014).
breast cancer (continued). "Reduced ATM mRNA abundance significantly correlates with aberrant methylation of the ATM promoter, which suggests that epigenetic silencing of ATM expression can occur in breast cancer." (PMID 25247188, 2014). "Even before the cloning of the ATM gene, it was evident that AT patients were affected by a high incidence of cancer, in particular thymus, breast cancer, lymphoma, and leukaemia." (PMID 25247188, 2014). "Previously, we performed case-control mutation screening studies of ATM, CHEK2, XRCC2, and RAD51 to clarify our understanding of their role in breast cancer susceptibility." (PMID 24894818, 2014). "A recent study also demonstrated that ATM facilitated invasion and lymph-node metastasis of breast cancer through the ATM-Snail pathway." (PMID 25386189, 2014). "In addition, there is little data on how systemic vitamin D status might interact with other known breast cancer risk factors including genetic (BRCA1, BRCA2, ATM), endocrine (estrogen, progesterone) and environmental (radiation, carcinogens) modulators of breast cancer development." (PMID 24982636, 2014). "Interestingly, the disease-causing nonsense variant in the ATM gene (p.E1978X), which is experimentally demonstrated to cause exon skipping, was originally reported as causing ataxia telangiectasia but has in addition been associated with breast cancer susceptibility." (PMID 24451234, 2014). "Only recently did an extensive study of gene mutational screening in patients affected by non-BRCA1/BRCA2 familial breast cancer clearly categorize ATM as a breast cancer gene." (PMID 25247188, 2014). "HOXB9 activates the TGFβ-ATM axis, leading to checkpoint activation and DNA repair, which engenders radioresistance in breast cancer cells." (PMID 25136922, 2014). "MiR-18a was over-expressed in breast cancer cell lines and tumors and its ectopic expression downregulated ATM by direct interaction with the 3′UTR of the gene." (PMID 24616890, 2014). "Intriguingly, we have shown a significant increase in the mRNA level of ATM in the WBC from the carries as compared to that in the breast cancer cases." (PMID 25403427, 2014). "Here we propose ATM-dependent changes in epigenetic regulation, in particular miRNA regulation of gene expression, play a role in the formation of breast cancer." (PMID 23741392, 2013). "While heterozygous carriers do not suffer from ataxia telangiectasia syndrome, they have an increased risk of developing heart disease, diabetes, and cancers, specifically breast cancer, compared to individuals with normal ATM expression levels." (PMID 23741392, 2013). "This indicates different features of ATM gene alterations between gastrointestinal and breast cancers." (PMID 24324828, 2013). "Mutational inactivation of the ATM gene has been demonstrated in mantle cell lymphoma, T-cell prolymphocytic leukemias, rhabdomyosarcomas, and gastric cancer, and ATM heterozygous state is more common in breast cancer patients than in the general population." (PMID 22485171, 2012).
breast cancer (continued). "After the identification of the ATM gene in 1995, numerous studies have demonstrated that individuals with ATM have a high incidence of malignancies, particularly breast cancer." (PMID 22276117, 2012). "We sequenced ATM and assessed gene expression levels in pre-treatment biopsies from 71 locally advanced breast cancers treated in the neoadjuvant setting with doxorubicin monotherapy or mitomycin combined with 5-fluorouracil." (PMID 22420423, 2012). "Suppression of miR-18a after the transfection of miR-18a inhibitor not only increased the expression of ATM in both breast cancer cell lines, but also dramatically increased the levels of phosphorylation levels of H2AX (γ-H2AX) and 53BP1 (p-53BP1)." (PMID 21980462, 2011). "In summary, the current study provides, for the first time, an important link between miR-18a-impaired DNA damage response and downregulation of ATM in breast cancer." (PMID 21980462, 2011). "In contrast to the findings with CD133+ positive cells from brain tumors, only slightly increased activation of downstream pathways was found primarily in BRCA1 although additional downstream targets of ATM in breast cancer CIC need to be examined." (PMID 21935375, 2011). "In our studies both the breast cancer cell lines MDA-M-231 and MCF-7 and the primary culture of patient breast cancer cells demonstrated enhanced expression of phosphorylated ATM in the CD44+/CD24−or low subpopulation after radiation." (PMID 21935375, 2011). "To further investigate the biological role of miR-18a in the progression of breast cancer, we examine the effect of miR-18a on the ATM expression in primary normal breast epithelial cells (NBECs)." (PMID 21980462, 2011). "Similar to the effect of ATM siRNA, overexpressing miR-18a in breast cancer cells reduced the DNA damage repair ability and the efficiency of homologous recombination-based DNA repair (HRR) and sensitized cells to γ-irradiation (IR) treatment." (PMID 21980462, 2011). "Four of the twelve breast cancer patients with severe late adverse normal tissue reactions to radiotherapy, patients 10, 11, 13 and 16, had levels of ATM protein ~35%, ~45%, ~8% and ~30%, respectively, compared to the highest expresser." (PMID 20678261, 2010). "The series had been used previously to determine the frequency of mutations in the BRCA1, ATM, NBS1 and CHEK2 genes as well as to characterize more common polymorphisms studied by the Breast Cancer Association Consortium." (PMID 21108795, 2010). "ATM deficiency results in lymphoid malignancies and BRCA1 mutation carriers have 50-85% life risk of developing breast cancer." (PMID 20175908, 2010). "Mutations in ATM, BRIP1, PALB2, CHEK2 and possibly NBS1, RAD50 are also associated with a moderately increased risk for breast cancer, and many low penetrance genes have recently been identified." (PMID 18706089, 2008). "Mutation frequencies reported in the literature indicate that about 10% of all women with breast cancer diagnosed before the age of 50 years have a germline mutation in BRCA1, BRCA2, ATM or CHEK2." (PMID 17428320, 2007).
breast cancer (continued). "Many of the known hereditary breast cancer genes such as BRCA1, BRCA2, CHEK2, ATM, and FANCJ/BRIP1 work together in a DNA repair pathway, raising the possibility that other genes in this pathway also predispose to breast cancer." (PMID 18053174, 2007). "We also screened the entire coding region and exon-intron boundaries of the ATM gene in 47 familial breast cancer patients and constructed haplotypes of the patients." (PMID 16914028, 2006). "Two ATM germline alterations (Ala2524Pro and 6903insA) reported in A-T families have been shown to segregate with breast cancer in these families." (PMID 16622469, 2006). "We calculated global P values for the association between the tagSNP haplotypes in the ATM, CHEK2 and ERBB2 genes and the risk of tumour-characteristic-defined breast cancer from logistic regression models." (PMID 17132159, 2006). "One SNP (rs228589) was significantly more prevalent among breast cancer cases compared with controls (P=4 × 10−9), and one discriminative ATM haplotype was significantly more prevalent among breast cancer cases (33.3%) compared with controls (3.8%), (P⩽10−10)." (PMID 16622469, 2006). "We then assessed the association of the tagSNPs in the ATM, CHEK2 and ERBB2 genes and their haplotypes with breast cancer survival and the risk of tumour-characteristic-defined breast cancer." (PMID 17132159, 2006). "Until now, common variation in the ATM, CHEK2 and ERBB2 genes has mainly been studied in relation to the overall risk of breast cancer, but the results have been inconclusive." (PMID 17132159, 2006). "However, whether rare ATM mutations, estimated to be present in about 0.4%–1% of the population, confer an increased breast cancer risk in the population, is beyond the scope of this study and has not been evaluated at a large scale in other studies yet either." (PMID 16914028, 2006). "The genes ATM, MRE11A, and XRCC4 were characterized using a panel of 94 unrelated female subjects (47 breast cancer cases, 47 controls) obtained from high-risk breast cancer families." (PMID 16091150, 2005). "In this study, we have described haplotypes and characterized the LD structure of the ATM, MRE11A, and XRCC4 genes using a panel of 94 subjects, including breast cancer cases from high-risk breast cancer families as well as controls." (PMID 16091150, 2005). "Recent reports suggest that two ATM gene mutations, 7271T>G and IVS10-6T>G, are associated with a high risk of breast cancer among multiple-case families." (PMID 14562025, 2003). "The incidence of breast cancer among heterozygous carriers in A-T families, along with the known biochemical interactions between the products of the ATM and BRCA1 genes, has suggested a role for ATM in breast cancer risk." (PMID 14562025, 2003). "There is also evidence that heterozygous carriers of the ATM gene are at increased risks of breast cancer." (PMID 11857015, 2002).
breast cancer (continued). "The findings of this study provide a proof of concept that pharmacological inhibition of ATM can enhance the cytotoxicity of Topo-II poisons such as Etoposide in breast cancer cells, supporting the rationale for targeting the DNA damage response as a therapeutic strategy." (PMID 41557625, 2026). "Background/Objectives: Contralateral breast cancer (CBC) is a significant concern among breast cancer survivors, particularly in those with moderator-high penetrance germline mutations such as BRCA1, BRCA2, CHEK2, and ATM." (PMID 41976331, 2026). "In contrast, patients with a pathogenic ATM variant do not have an increased risk of developing contralateral breast cancer." (PMID 41528496, 2026). "The identification of ATM and DNMT3A as high-impact mutations may hold particular relevance for early detection and risk stratification in breast cancer." (PMID 41382403, 2025). "This approach is particularly valuable when counseling individuals with variants in moderate-penetrance breast cancer genes like CHEK2, ATM, RAD51C, RAD51D, and BARD1, since the relative effect of risk factors is expected to be higher than in individuals with high-penetrance PVs." (PMID 40805171, 2025). "Another study indicated that the estimated lifetime breast cancer risk for BRCA1 and BRCA2 PV carriers increased with higher PRS313 scores, though the observed effect was smaller than in the general population or among carriers of PVs in ATM, CHEK2, and PALB2." (PMID 40296163, 2025). "Moreover, women with a pLOF in ATM or CHEK2 and ranking in the top 50% of the PRS displayed a high risk (39.2% probability of breast cancer at age 70), whereas their counterparts in the bottom 50% of the PRS were not at high risk (14.4% probability at age 70)." (PMID 39669587, 2024). "Mutation spectrum of ATM, CHEK2, PALB2, and XRCC2 genes in patients with breast cancer." (PMID 38784039, 2024). "Both the ATM, PALB2 and CHEK2 genes are breast cancer susceptibility genes of moderate penetrance." (PMID 38504328, 2024). "The role of ATM and RB1 in cell cycle control and cellular senescence, as well as their connection to trastuzumab resistance, offers important insights into the mechanisms underlying therapeutic resistance in breast cancer." (PMID 39655080, 2024). "Because many genes cause breast cancer predisposition, and because penetrance is low, proband counting does not apply to ATM." (PMID 38854136, 2024). "On the whole studies to date do not suggest that women with breast cancer and an ATM mutation should avoid radiotherapy or to reduce the dose." (PMID 39543654, 2024). "Besides, rare variants in other genes like ATM, CHEK2, CDH1, PALB2, RAD50, and RAD51C have been detected mainly in the breast cancer subgroup." (PMID 39148954, 2024). "An alternative approach (strategy #2) could entail discontinuing the ascertainment of family history of breast cancer and instead refer all women with a pathogenic variant in BRCA1, BRCA2, PALB2, ATM, and CHEK2 or a PRS in the top 10%." (PMID 39669587, 2024). "This could explain their immature application in breast cancer and special concerns should be given to ensure that the therapeutic benefits of ATM inhibitors outweigh the therapeutic risks." (PMID 39334297, 2024).